BORCS5 (BLOC-1 related complex subunit 5)
Description:
As part of the BORC complex may play a role in lysosomes movement and localization at the cell periphery. Associated with the cytosolic face of lysosomes, the BORC complex may recruit ARL8B and couple lysosomes to microtubule plus-end-directed kinesin motor. Thereby, it may indirectly play a role in cell spreading and motility.
Synonyms: LOH12CR1; LOH1CR12
Tractability: Antibody: its Gene Ontology location is reachable by antibodies, with high confidence. PROTAC: ubiquitination databases record sites on it.
Gene: Protein-coding gene on chromosome 12 (12,357,078 to 12,471,233, forward strand). Ensembl gene ENSG00000165714.
Subcellular location: Lysosome membrane
Subcellular location (Human Protein Atlas): Plasma membrane; Vesicles
Gene Ontology:
Molecular function: protein binding
Biological process: lysosome localization; organelle transport along microtubule; positive regulation of anterograde synaptic vesicle transport; regulation of endosome size; regulation of lysosome size
Cellular component: BORC complex; cytoplasmic side of lysosomal membrane; lysosomal membrane; membrane; plus-end kinesin complex; synaptic vesicle membrane; axon; lysosome
Genetic constraint (gnomAD): Loss-of-function variants: 17 observed, 23.07 expected, observed/expected ratio (o/e) 0.74, 90% interval 0.5 to 1.11. The upper end of that interval is the gene's LOEUF score, 1.11, which puts it in group 4 of 6, group 1 being the genes least tolerant of losing a copy. Missense variants: 247 observed, 266.76 expected, observed/expected ratio (o/e) 0.93, 90% interval 0.83 to 1.03. Synonymous variants: 117 observed, 105.03 expected, observed/expected ratio (o/e) 1.11, 90% interval 0.96 to 1.3.
Homologues: Orthologues: chimpanzee BORCS5 (99% identical), macaque BORCS5 (98% identical), guinea pig BORCS5 (97% identical), rabbit BORCS5 (96% identical), dog BORCS5 (96% identical), pig BORCS5 (96% identical), mouse Borcs5 (94% identical), rat Borcs5 (93% identical), tropical clawed frog borcs5 (81% identical), zebrafish borcs5 (78% identical), Drosophila melanogaster BORCS5 (35% identical), Caenorhabditis elegans sam-4 (26% identical).
Diseases named in the same sentence as BORCS5 in open-access papers:
BORCS5 is named in the same sentence as 20 diseases in open-access papers, as found by Europe PMC text mining. Sharing a sentence is not in itself a finding about the gene and the disease. The quoted sentences say what the papers report.
microcephaly (2 papers, 2025 to 2026). A congenital or acquired developmental disorder in which the circumference of the head is smaller than normal for the person's age and sex. "Borcs5 KO in zebrafish resulted in microcephaly, motor deficits, and increased seizure susceptibility, mirroring the patients' clinical presentation." (PMID 42012897, 2026). "Borcs5 knockout in zebrafish exhibited microcephaly, motor deficits, and seizures, mirroring the patients’ clinical presentation." (PMID 40385417, 2025).
neuroaxonal dystrophy (2 papers, 2025 to 2026). A nonspecific term referring both to the pathologic finding of swelling of distal portions of axons in the brain and to disorders which feature this finding. "Carriers of homozygous protein-truncating variants (PTVs), resulting in complete loss of BORCS5, presented with prenatally lethal arthrogryposis multiplex congenita, brain malformations, and neuropathological evidence of neuroaxonal dystrophy." (PMID 42012897, 2026).
developmental delay (1 paper, 2020). "A recent study revealed the presence of a single-nucleotide, splice-acceptor variant (NM_058169.4:c.203–1G>T) of BORCS5 in a patient with global developmental delay, corpus callosum agenesis, seizures, polymicrogyria, and abnormality of the cerebral cortex." (PMID 32553155, 2020).
Dystonia (1 paper, 2025). An abnormally increased muscular tone that causes fixed abnormal postures. "The role of BORCS5 in lysosomal function may have important implications for other neurological disorders characterized by lysosomal dysfunction, including PD and dystonia." (PMID 40385417, 2025).
respiratory failure (1 paper, 2023). The significant impairment of gas exchange within the lungs resulting in hypoxia, hypercarbia, or both, to the extent that organ tissue perfusion is severely compromised. "Interestingly, the Borcs5-KO mouse showed atelectasis of the lungs and died of respiratory failure within 1 h of birth." (PMID 37936104, 2023).
neurological disorders (1 paper, 2025). "We provide genetic and functional evidence establishing BORCS5 as a human disease-associated gene responsible for a severe neurological disorder characterized by a broad spectrum of phenotypes, from profound neurodevelopmental defects to infantile-onset neurodegeneration." (PMID 40385417, 2025). "The impact of BORCS5 variants on different aspects of lysosomal biology may underlie the different clinical presentations observed in individuals with BORCS5-related neurological disorders." (PMID 40385417, 2025).
BORCS5 also shares sentences with these, for which no sentence is quoted: acute lymphoblastic leukemia (1 paper); arthrogryposis multiplex congenita (1); cancer (1); developmental epileptic encephalopathy (1); ependymoma (1); epilepsy (1); fucosidosis (1); gangliosidosis (1); lysosomal storage disorders (1); movement disorder (1); Niemann-Pick disease type A (1); polymicrogyria (1); tumor (1); Ventriculomegaly (1).